REN (renin)
Diseases named in the same sentence as REN in open-access papers (continued):
Sharing a sentence is not in itself a finding about the gene and the disease.
endothelial dysfunction (506 papers, 2008 to 2026). In vascular diseases, endothelial dysfunction is a systemic pathological state of the endothelium (the inner lining of blood vessels) and can be broadly defined as an imbalance between vasodilating and vasoconstricting substances produced by (or acting on) the endothelium. "Emerging evidence supports precision approaches targeting individuals with severe deficiency, high renin activity, early endothelial dysfunction, or specific genetic profiles, potentially in combination with lifestyle or pharmacologic interventions." (PMID 41683321, 2026). "In these populations, PCS has been linked across studies to processes including endothelial dysfunction, chronic low-grade inflammation, autonomic imbalance, and potential dysregulation of the renin-angiotensin-aldosterone system (RAAS)." (PMID 41732619, 2026). "Key pathophysiological mechanisms underlying RHF include renin-angiotensin system activation, heightened sympathetic nervous system activity, and endothelial dysfunction, contributing to increased glomerular permeability and capillary hydraulic pressure." (PMID 41164368, 2025). "In parallel, elevated uric acid levels are associated with endothelial dysfunction, activation of the renin–angiotensin system, and promotion of a pro-inflammatory milieu, thereby reflecting heightened oxidative stress and metabolic demand." (PMID 41156285, 2025). "Several mechanisms associated with endothelial dysfunction have been reported, including increased oxidative stress, inflammation, the dysregulation of the sympathetic nervous system and/or the renin-angiotensin system." (PMID 40500724, 2025). "This association is due to the significant activation of the renin–angiotensin system, endothelial dysfunction, and sympathetic activation." (PMID 38399430, 2024). "This dysregulation of the Renin-Angiotensin-Aldosterone-System causes endothelial dysfunction not only by ROS, but also by overexpressing various factors and receptors, such as COX-2, VEGF, and LOX-1." (PMID 38255892, 2024). "Elevated uric acid can also lead to kidney disease by causing endothelial dysfunction, activation of the renin-angiotensin-aldosterone system (RAAS), inflammation, and oxidative stress." (PMID 39438792, 2024). "More specifically, abdominal obesity is associated with high sympathetic nervous activity, endothelial dysfunction, abnormalities of the renin angiotensin aldosterone system, and a chronic inflammatory state." (PMID 39797099, 2024). "Hyperinsulinemia in MetS, results in excessive renal sodium maintenance and increased blood pressure, which in turn can cause several renal diseases by activation of the renin-angiotensin-aldosterone system, adipokine imbalance, and endothelial dysfunction." (PMID 37670399, 2023). "In summary, endothelial dysfunction, atherosclerosis, and the status of full-blown cardiovascular disease are associated with a chronic activation of the local and/or circulating renin–angiotensin–aldosterone system (RAAS) and an uncoupled eNOS." (PMID 36719770, 2023). "Cystic enlargement probably causes parenchymal hypoxia, renin secretion, and endothelial dysfunction." (PMID 37043156, 2023). "This process can cause renal ischemia with renin release, complicated by endothelial dysfunction, reduced NO, and sympathetic tone activation." (PMID 37043156, 2023). "Neurohormonal changes such as autonomic dysfunction and activation of the renin-angiotensin-aldosterone system are also implicated, as are endothelial dysfunction and inflammation." (PMID 35893744, 2022). "Fourth, the renin–angiotensin system imbalance and inflammatory process produce endothelial dysfunction with eNOS uncoupling, causing a decrease in NO production and consequently a decrease in cGMP." (PMID 34980198, 2022).
endothelial dysfunction (continued). "Lipoprotein accumulation, inflammation, oxidative stress, endothelial dysfunction, oxidative stress, and the renin–angiotensin–aldosterone (RAA) system are all causatives motives in AS, whereashypertrophy and myocardial fibrosis are symptomatic." (PMID 35455758, 2022). "The physiological role of UA as an oxidant is supported by a number of in vitro and in vivo studies reporting that intracellular UA causes inflammation, oxidative stress, endothelial dysfunction, and activation of the renin–angiotensin–aldosterone system." (PMID 34078313, 2021). "BP increasing the effect of PTH except in regulating the 25-OH vitamin D level can be due to increasing renin release from the kidney, causing endothelial dysfunction, increasing arterial stiffness, and activating the sympathetic system." (PMID 34946242, 2021). "A high serum UA level is associated with oxidative stress, inflammatory response, endothelial dysfunction, development of metabolic syndrome, and activation of the renin-angiotensin system in CKD patients." (PMID 32401146, 2020). "Their shared underlying mechanisms included insulin resistance, endothelial dysfunction, inflammation, oxidative stress, and activation of the renin-angiotension system (RAS)." (PMID 33204732, 2020). "Available data indicate that COVID-19 and cardiovascular disease share pathomechanisms and risk factors which include ACE2 receptor invasion and renin-angiotensin system signaling, oxidative stress, systemic inflammation, and endothelial dysfunction." (PMID 33282075, 2020). "Common underlying mechanisms have been suggested to account for this association, such as inflammation, insulin resistance, endothelial dysfunction and renin-angiotensin-aldosterone system activation." (PMID 33008317, 2020). "Testosterone, in pregnant rats, also causes endothelial dysfunction and exaggerated vasoconstriction to contractile agonists and dysregulates renin-angiotensin system with exaggerated vascular smooth muscle sensitivity to angiotensin II." (PMID 30325182, 2018). "It is postulated that the endothelial dysfunction caused by activation of the renin-angiotensin-aldosterone system (RAAS) has a central role." (PMID 23448537, 2013). "In a previous report, vascular injury and endothelial dysfunction due to modulation of renin-angiotensin and endothelinergic systems were implicated in radiation exposure-induced heart disease." (PMID 23840332, 2013). "The mechanism by which elevated uric acid causes endothelial dysfunction, is inhibiting nitric oxide synthetase, activating the renin–angiotensin system and causing proinflammation and resultant endothelial dysfunction." (PMID 25340142, 2013). "Cell biology and animal studies indicated that chronic hyperuricemia can induce vascular smooth muscle cell hyperplasia, activate the local renin-angiotensin system, stimulate inflammatory makers, and cause endothelial dysfunction." (PMID 23637835, 2013). "Deficiencies in vitamin D may lead to endothelial dysfunction, increased oxidative stress, and activation of the renin–angiotensin–aldosterone system (RAA), which contributes to increased vascular resistance and elevated blood pressure." (PMID 41059575, 2025). "In addition, malignant hypertension triggers endothelial injury via sheer stress, activating RAAS (renin-angiotensin-aldosterone system) and causing release of angiotensin II, which directly causes damage to vessels resulting in endothelial dysfunction." (PMID 39130838, 2024). "With the stimulation of renin angiotensin aldosterone system, the elevated blood pressure leads to endothelial dysfunction and microvascular ischemia, glomerulosclerosis, loss of nephron, and decline of renal function, which in turn causes the occurrence of renal cyst." (PMID 38172931, 2024).
endothelial dysfunction (continued). "Uric acid can interfere with the synthesis of nitric oxide, inhibit the bioavailability of nitric oxide, activate the renin-angiotensin system, promote vascular smooth muscle cell proliferation and platelet aggregation, and eventually cause endothelial dysfunction." (PMID 37940848, 2023). "Increases in turnover of the extracellular matrix may cause endothelial dysfunction, abnormal renin‐angiotensin‐aldosterone system activation, and atherogenesis." (PMID 37609985, 2023). "In addition, insulin resistance contributes to AS by causing endothelial dysfunction, immunodeficiency, and abnormal renin–angiotensin–aldosterone system activation." (PMID 37755998, 2023). "High eGFR may be associated with dysfunction of the renin-angiotensin system, low-grade vascular or systemic inflammation, endothelial dysfunction, and increased arterial stiffness." (PMID 38107638, 2023). "In addition, endothelial dysfunction and microangiopathy have been proposed as underlying mechanisms, as have been alterations of the renin-angiotensin-aldosterone system." (PMID 35594336, 2022). "However, it is assumed that complex pathophysiological factors such as adipocytokines, insulin resistance, renin–angiotensin–aldosterone activation, endothelial dysfunction, and oxidative stress, play a role in this association." (PMID 35778682, 2022). "The potential mechanism underlying this procedure may be related to inflammation, endothelial dysfunction and the activation of the renin-angiotensin system." (PMID 36235845, 2022). "The other mechanism involves ACE2; the depletion of ACE2 by SARS-CoV-2 could cause an imbalance of the renin angiotensin system, which might result in endothelial dysfunction and ischemic stroke." (PMID 34573160, 2021). "Basic research can help us understand the specific mechanisms of this relationship: higher UA levels cause endothelial dysfunction, activation of the renin-angiotensin aldosterone system, vascular injury, tubulointerstitial inflammation, and elevated blood pressure." (PMID 33765101, 2021). "The possible mechanisms behind the association with blood pressure increases include endothelial dysfunction, intracellular calcium accumulation, stimulation of the renin-angiotensin-aldosterone system, elevated sympathetic activity, vasoconstriction, and elevated oxidative stress." (PMID 33005509, 2020). "These can cause endothelial dysfunction, renin-angiotensin-aldosterone activation." (PMID 32961936, 2020). "However, activated renin–angiotensin system was reported to be closely associated with endothelial dysfunction and vascular oxidative stress in autoimmune and inflammatory disease models." (PMID 30761252, 2019). "XOR-derived free radicals may cause endothelial dysfunction and vasoconstriction by lowering nitric oxide availability and stimulating the upregulation of the renin-angiotensin system, which plays a pivotal role in inflammatory signalling." (PMID 29070821, 2017). "Mechanisms of this association include activation of the renin-angiotensin-aldosterone system by increasing sympathetic activity, insulin resistance, leptin resistance, increased procoagulant activity, and endothelial dysfunction, which may lead to HTN and cardiovascular disease." (PMID 38566160, 2024). "Moreover, high eGFR may be associated with dysfunction of the renin-angiotensin system, low-grade vascular or systemic inflammation, endothelial dysfunction, and increased arterial stiffness." (PMID 37692776, 2023). "However, previous studies have shown that high FGF23 concentration may be associated with endothelial dysfunction and activation of the renin-angiotensin-aldosterone system (RAAS)." (PMID 37593148, 2023). "Moreover, activation of sympathetic nerves and the renin-angiotensin-aldosterone system, chronic inflammation, oxidative stress, and endothelial dysfunction may also be associated with adverse clinical outcomes in patients with anemia and CKD." (PMID 33182592, 2020).
endothelial dysfunction (continued). "According to a number of reports in the literature, endothelial dysfunction, atherosclerosis, and the late cardiovascular complications of these adverse phenomena are associated with a chronic activation of the local and/or circulating renin-angiotensin-aldosterone system (RAAS)." (PMID 30621010, 2019). "These pathways include the regulation of inflammatory responses, oxidative stress, insulin resistance, endothelial dysfunction, vascular smooth muscle cell proliferation, and activation of the renin-angiotensin system." (PMID 40554493, 2025). "Drugs such as cyclooxygenase 2 inhibitors and inhibitors of the renin-angiotensin system can alleviate endothelial dysfunction by targeting endothelial inflammation." (PMID 40230380, 2025). "The pathophysiology of CKM involves a multitude of factors, including inflammation, endothelial dysfunction, and hormonal imbalances, such as the renin-angiotensin-aldosterone system (RAAS)." (PMID 40959488, 2025). "High-fructose diet stimulates the sympathetic nervous system and renin–angiotensin–aldosterone (RAAS) activity, of which both are responsible for endothelial dysfunction and are associated with salt-sensitive hypertension." (PMID 40806096, 2025). "The pathophysiology of pediatric hypertension involves a complex interplay of arterial stiffness, endothelial dysfunction, metabolic disturbances, activation of the renin–angiotensin–aldosterone system, and immune dysregulation." (PMID 40927078, 2025). "The underlying mechanisms involve a combination of cytokine-mediated inflammation, endothelial dysfunction, microvascular injury, and dysregulation of the renin–angiotensin–aldosterone system (RAAS)." (PMID 41462903, 2025). "Of course, endothelial dysfunction, arterial stiffness, renin-angiotensin-aldosterone (RAA) system activation, and cardiac dysfunction also have been reported as factors contributing to exercise-induced BP elevation, in addition to sympathetic hyperactivity." (PMID 39639127, 2025). "On the other hand, uric acid can mediate endothelial dysfunction through the activation of the renin-angiotensin system (RAS) and by inducing the proliferation and modification of vascular smooth cells, eventually leading to glomerulosclerosis." (PMID 39852354, 2025). "Research evidence suggests that hyperuricemia promotes the development of ASCVD through mechanisms such as inducing inflammation, endothelial dysfunction, vascular smooth muscle cell proliferation, and activation of the renin-angiotensin system." (PMID 40486823, 2025). "A key proposed mechanism linking gout to CVD and CKD is via hyperuricemia-induced effects, including endothelial dysfunction, renin-angiotensin system activation, and vascular and tubulointerstitial damage." (PMID 40519626, 2025). "This increased risk is mediated through immune dysfunction, chronic inflammation, hyperglycemia, dysregulation of renin-angiotensin system dysregulation, endothelial dysfunction, and hypercoagulability." (PMID 40430154, 2025). "This sustained hypoxic state is a potent pathological stimulus, known to induce endothelial dysfunction and activate the renin–angiotensin–aldosterone system (RAAS), leading directly to blood pressure elevation." (PMID 41477189, 2025). "It is a complex syndrome characterized by activation of the sympathetic nervous system and the Renin–Angiotensin–Aldosterone (RAAS) axis as well as endothelial dysfunction, oxidative stress, and inflammation." (PMID 40299538, 2025). "It has been associated with a loss of the normal dipping pattern, increased peripheral vascular resistance, subclinical endothelial dysfunction, and an altered response of the renin–angiotensin system." (PMID 40649890, 2025). "Other contributing mechanisms include overactivation of the renin-angiotensin-aldosterone system, increased oxidative stress and inflammation, endothelial dysfunction, metabolic acidosis, anemia, and insulin resistance." (PMID 40406753, 2025).
endothelial dysfunction (continued). "This phenomenon is mediated by various mechanisms including endothelial dysfunction, volume expansion, cytokine secretion, sympathetic nervous system activation, anemia, inflammation, and activation of the renin-angiotensin-aldosterone system." (PMID 40255329, 2025). "In individuals with DM, activation of the renin–angiotensin–aldosterone system triggers vasoconstriction, inflammation, and oxidative stress, all leading to the worsening of endothelial dysfunction and the progression of atherosclerosis." (PMID 41470244, 2025). "Persistent inflammation, endothelial dysfunction, and renin–angiotensin system imbalance are key features shared between acute COVID-19 and long-term complications." (PMID 41471341, 2025). "BNP levels increase with age due to impaired ventricular compliance, endothelial dysfunction, and increased preload and afterload due to the increased activity of the renin–angiotensin–aldosterone system." (PMID 40283562, 2025). "Acting in different combinations and sequences, they trigger three main pathogenic processes: sympathetic nervous system hyperactivity, renin–angiotensin–aldosterone system activation, and endothelial dysfunction." (PMID 39767388, 2024). "In DM, chronic hyperglycemia, insulin resistance, and dyslipidemia further contribute to endothelial dysfunction through various mechanisms, including increased oxidative stress, inflammation, and activation of the renin-angiotensin-aldosterone system." (PMID 39039512, 2024). "In fact, (low grade) inflammation/pro-inflammatory cytokines have been shown to activate the renin-angiotensin-aldosterone system, even in local vascular tissue, leading to endothelial dysfunction and vascular stiffening." (PMID 38410507, 2024). "Reduced muscle tissue can lead to insulin resistance, endothelial dysfunction, inflammation, oxidative stress, activation of the renin–angiotensin–aldosterone system (RAAS), and autophagy dysregulation in adipocytes." (PMID 38549547, 2024). "Oxidative stress is well established as a key regulator of age-induced endothelial dysfunction and the renin–angiotensin–aldosterone system (RAAS)." (PMID 39459569, 2024). "Angiotensin II (Ang II) is an effective vasoconstriction peptide, a major effector molecule of the renin–angiotensin–aldosterone system (RAAS) and one of the important causes of endothelial dysfunction." (PMID 39595632, 2024). "Several mechanisms can contribute to postmenopausal hypertension, such as endothelial dysfunction, inappropriate activation of renin‐angiotensin and sympathetic systems, oxidative stress, inflammatory mediators, dyslipidemia, and weight gain." (PMID 38650726, 2024). "It is multifactorial and involves fluid and sodium retention, insulin resistance, the sympathic nervous system activation, the renin–angiotensin–aldosterone axis stimulation, and other mechanisms like adipokines release and endothelial dysfunction." (PMID 38337357, 2024). "Elevated BMI also emerged as a strong predictor, aligning with research linking BMI to HTN and cardiovascular diseases through mechanisms like renin-angiotensin system activation and endothelial dysfunction." (PMID 39715219, 2024). "The role of low sodium or high potassium intake modulates renin-angiotensin system activity, arterial stiffness, and endothelial dysfunction." (PMID 39273236, 2024). "AFD-related vascular pathology includes increased renin-angiotensin system activation, endothelial dysfunction, and smooth muscle cell proliferation, resulting in IMT increase." (PMID 39125842, 2024). "This activates the renin-angiotensin-aldosterone system (RAAS) and causes endothelial dysfunction and oxidative stress." (PMID 38910690, 2024). "The renin-angiotensin-aldosterone system regulates BP, sodium retention, pressure natriuresis, salt sensitivity, vasoconstriction, endothelial dysfunction, and vascular injury." (PMID 37513599, 2023).